RN7SKP291 (RN7SK pseudogene 291)
Gene: Miscellaneous RNA gene on chromosome 1 (55,376,526 to 55,376,852, reverse strand). Ensembl gene ENSG00000199831.
Homologues: Orthologues: chimpanzee 7SK (98% identical). Paralogues in human: 7SK (73% identical), RN7SKP203 (71% identical), RN7SKP118 (70% identical), RN7SKP255 (70% identical), RN7SKP124 (70% identical), RN7SKP176 (70% identical), RN7SKP79 (70% identical), RN7SKP217 (69% identical), RN7SKP78 (69% identical), RN7SKP133 (69% identical), RN7SKP180 (69% identical), RN7SKP187 (69% identical), and 283 more.
Diseases named in the same sentence as RN7SKP291 in open-access papers:
RN7SKP291 is named in the same sentence as 1 disease in open-access papers, as found by Europe PMC text mining. Sharing a sentence is not in itself a finding about the gene and the disease.
RN7SKP291 shares sentences with these, for which no sentence is quoted: cancer (1 paper).